ESAM (endothelial cell adhesion molecule)
Description:
Can mediate aggregation most likely through a homophilic molecular interaction.
Synonyms: W117m; NEDIHSS
Tractability: Antibody: UniProt places it where antibodies can reach, with high confidence; its Gene Ontology location is reachable by antibodies, with high confidence; UniProt predicts a signal peptide or a membrane-spanning region. PROTAC: ubiquitination databases record sites on it.
Gene: Protein-coding gene on chromosome 11 (124,752,583 to 124,762,315, reverse strand). Ensembl gene ENSG00000149564.
Subcellular location: Cell junction, adherens junction; Cell junction, tight junction; Cell membrane
Subcellular location (Human Protein Atlas): Cell Junctions; Cytosol
Pathways (Reactome):
Hemostasis: Cell surface interactions at the vascular wall
Gene Ontology:
Molecular function: cell-cell adhesion mediator activity; identical protein binding; protein binding
Biological process: bicellular tight junction assembly; cell-cell adhesion; intracellular protein localization; regulation of actin cytoskeleton organization; regulation of actin filament polymerization; homophilic cell-cell adhesion; maintenance of blood-brain barrier
Cellular component: cell-cell junction; plasma membrane; protein-containing complex; adherens junction; bicellular tight junction
Genetic constraint (gnomAD): Loss-of-function variants: 26 observed, 35.75 expected, observed/expected ratio (o/e) 0.73, 90% interval 0.53 to 1.01. The upper end of that interval is the gene's LOEUF score, 1.01, which puts it in group 4 of 6, group 1 being the genes least tolerant of losing a copy. Missense variants: 478 observed, 512.38 expected, observed/expected ratio (o/e) 0.93, 90% interval 0.87 to 1.01. Synonymous variants: 216 observed, 220.15 expected, observed/expected ratio (o/e) 0.98, 90% interval 0.88 to 1.1.
Homologues: Orthologues: chimpanzee ESAM (99% identical), macaque ESAM (96% identical), pig ESAM (82% identical), dog ESAM (80% identical), mouse Esam (73% identical), rat Esam (69% identical), guinea pig ESAM (67% identical), tropical clawed frog esam (43% identical), zebrafish esamb (39% identical), zebrafish esama (38% identical), zebrafish gpa33a (17% identical). Paralogues in human: IGSF11 (27% identical), VSIG2 (26% identical), VSIG1 (24% identical), CLMP (24% identical), CXADR (23% identical), VSIG8 (20% identical), GPA33 (18% identical), MXRA8 (16% identical), JAM3 (16% identical), F11R (15% identical), JAM2 (15% identical), VSTM2B (12% identical), and 2 more.